IL6 (interleukin 6)
Diseases named in the same sentence as IL6 in open-access papers (continued):
Sharing a sentence is not in itself a finding about the gene and the disease.
colitis (continued). "Collectively, cinacalcet reduces production of the inflammatory cytokines TNFα, IL-1β, and IL-6 in a DSS-induced colitis model." (PMID 34880751, 2021). "Some proinflammatory cytokines and mediators (e.g., TNF-a, IL-6 and IL-1β) have been used as markers of anti-inflammatory activity in a dextran sodium sulfate colitis mouse model, and IL-10 has anti-inflammatory properties and functions in immune regulation." (PMID 34490398, 2021). "The upregulation of miR‐223 by agomir administration alleviated colonic inflammation in a DSS‐induced colitis model, which was likely mediated by inhibiting the production of pro‐inflammatory cytokines via the IL‐6/STAT3 signaling pathway." (PMID 33332758, 2021). "Oral administration of PCA improved symptoms of DSS-induced colitis in rats and prevented the increase in the pro-inflammatory cytokines IL-1β, IL-6, and TNF-α that was seen in controls." (PMID 34073220, 2021). "According to our current findings, PF-04447943 also protects colon from colitis by reversing the Th17/Treg cells balance with suppression of DC and downregulation of IL-17, 1L-12/23, and IL-6." (PMID 33967779, 2021). "Mouse model with DSS-induced colitis displayed an extensive inflammatory state, manifested by a significant elevation of pro-inflammatory cytokines such as IL-6 in the blood, colon, and brain, and elevated LBP in the colon." (PMID 34806521, 2021). "The results showed that OC-B-BBR significantly ameliorated colitis symptoms and colon damage by regulating the expression levels of IL-6 and remodeling gut microbiota." (PMID 33959013, 2021). "Their exposures also increased TNF-α and IL-6 expression and NF-κB+/Iba1+ cell population in the colon and Proteobacteria population in the gut microbiota, leading to colitis and gut microbiota perturbation." (PMID 33731795, 2021). "Mice that were fed American ginseng showed a significant improvement in DSS-induced colitis symptoms, and had reduced levels of the pro-inflammatory cytokines IL-1β and IL-6." (PMID 34073220, 2021). "The observed results exhibited significantly (p < 0.001) increased concentrations of IL-6 in colitis rats." (PMID 33802553, 2021). "This further convinced their former observation that the colitis mice with anti-IL-6 mAb treatment beginning at the onset of co-housing led to significantly greater weight loss and decrease in crypt number over time compared with control group 108." (PMID 33390844, 2021). "In comparison to IL-10 and IL-22, we observed that IL-6 was the most abundantly produced cytokine during DSS-induced colitis development in wild-type mice as well as in mice with reduced STAT3 activity." (PMID 33673239, 2021). "Oral administration of TFA at or after modeling significantly attenuates the production of IL-6 and IL-17 in the sera and the tissue of colitis mice, and increased the Treg cell cytokines such as IL-10 and TGF-β." (PMID 35002710, 2021). "The inflammatory factors IL-21, IL-17 A, IL-6 were up-regulated significantly in colitis model group in contrast to control, while miRNA-182-5p inhibitor alleviated the increase of IL-21, IL-17 A, and IL-6." (PMID 34623552, 2021). "In a previous study, Bacteroides was positively correlated with pro-inflammatory cytokine IL-6 in DSS-induced colitis mice." (PMID 34867926, 2021). "The inflammatory cytokines TNF-α and IL-6 are well-known therapeutic targets in IBD that contribute to the deterioration of the colitis condition." (PMID 34630408, 2021). "Several studies have illustrated that blocking IL-6 signal transduction in chronic intestinal inflammation leads to remarkable inhibition of colitis activity." (PMID 34956375, 2021). "Previous studies described that inflammation of the colon increases the activity of inflammation-related cytokines including TNF-α, IL-1β, and IL-6 in serum and colon tissues in murine colitis." (PMID 34066160, 2021).
colitis (continued). "In the present study, OF.Cr treatment resulted in significantly decreased release of TNF-α and IL-6, as compared with the AA-induced colitis rats." (PMID 33802553, 2021). "Cytokines related to colitis pathology (such as IL-6, IL-1β, IFNγ, and IL-17a) are significantly inhibited in the colon tissue of exosome-treated model mice." (PMID 34683937, 2021). "YST from low dose to high dose gradually decreased the levels of TNF-α, IL-1β, and IL-6 in colon tissues of colitis mice." (PMID 34055024, 2021). "To understand the role of Lgals3bp in inflammatory responses during colitis, we measured the expression of pro-inflammatory cytokines, such as IL-6, TNF-α, and IL-β using RT-qPCR." (PMID 33824294, 2021). "In another rat model, VK deficiency also resulted in exacerbation of murine dextran sulfate sodium (DSS)-induced colitis by IL-6 production from B cells." (PMID 35069573, 2021). "In the present study, exposure to RS raised neuroinflammation and colitis: it induced IL-6 expression and NF-κB activation in the hippocampus and myeloperoxidase activity and NF-κB activation in the colon." (PMID 34391441, 2021). "In this study, we attempted to determine the role of miR‐223 in dextran sodium sulfate (DSS)‐induced colitis and explore the involvement of the IL‐6/STAT3 pathway in the development of intestinal mucosal inflammation." (PMID 33332758, 2021). "The knock-down of miR-155 protects the experimental colitis mice by decreasing IFNγ, TNFα, IL-6, IL-12 and IL-17 production, reducing Th1 response and suppressing the T-cells activation by DCs." (PMID 33921348, 2021). "IL-6/STAT3 signaling has been identified necessary for the survival of intestinal epithelial cells, which also plays an important role in colitis-associated tumorigenesis." (PMID 34689842, 2021). "Accordingly, we measured the concentration of the IL-6 protein in serum, and found that the serum IL-6 concentration was obviously increased with the onset of the colitis and then significantly suppressed by KNT-127 administration." (PMID 34630408, 2021). "Treatment with alliin in DSS-induced colitis mice reduced colon damage, showing a decrease in pro-inflammatory cytokines (IL-6, IL-1β, and TNF-α) in colonic tissue." (PMID 34068714, 2021). "TNBS-induced colitis was accompanied by elevated colonic expression of genes encoding representative proinflammatory cytokines (TNF-α and IL-6) and enzymes (COX-2), which was suppressed by TauCl administration." (PMID 33803551, 2021). "Lactic acid and SyBE also significantly reduced the contents of pro-inflammatory cytokines, such as TNF-α, IL-6, and IL-1β, in serum, that promote the development of colitis." (PMID 34899735, 2021). "This has been confirmed in mice with a dextran sodium sulfate (DSS)-induced colitis where gallic acid significantly inhibited the colonic inflammation by affecting NFᴋB and interleukin 6 (IL-6)/pSTAT3Y705 activation." (PMID 34944544, 2021). "ELISA data showed that the expression levels of TNF-α, IL-1α, IL-6, and IL-8 in colitis mice were significantly reduced compared with those in control samples." (PMID 34456974, 2021). "Emerging experimental and clinical data have indicated that pro-inflammatory cytokines such as TNF-α, IFN-α and IL-6 play crucial roles in pathogenesis of colitis." (PMID 33461587, 2021). "Anti-IL6 was administered in one case of pneumonitis grade 2 and colitis grade 3, with toxicity resolution." (PMID 34208218, 2021). "In a study using the DSS-induced colitis model, loss of miR-155 was found to ameliorate colitis by reducing TNF-α and interleukin- 6, -12 and -17 in the tissue." (PMID 33647883, 2021). "A further study showed that TpH2−/− mice with DSS-induced colitis had increased severity of disease characterized by an increased secretion of the pro-inflammatory cytokines IL-1β, IL-6 and, TNF-α, and high mortality rates in comparison to the wild type." (PMID 34502396, 2021).
colitis (continued). "These FMTs inhibited the RS-induced colitis: they decreased myeloperoxidase activity and IL-6 expression and suppressed NF-κB activation." (PMID 34391441, 2021). "The combination of carboxylmethyl chitosan modified with phenylboronic esters and berberine can significantly improve the symptoms of colitis and colon damage by regulating IL-6 expression and remodeling the intestinal microbiota." (PMID 35046810, 2021). "In murine models, genetic ablation of Irf4 protected mice from experimental colitis because of decreased production of IL-6." (PMID 32369982, 2020). "C-reactive protein (CRP) level and IL-6 were observed to reflect the clinical course of colitis clearly, which exposed the potentiality nivolumab-related toxicities predictive value." (PMID 33123120, 2020). "In the present study, it was observed that the levels of CRP, IFN-γ, TNF-α, and IL-6 were elevated in mice plasma with DSS-induced colitis." (PMID 32419794, 2020). "Blocking the activation of IL-1β attenuates the symptoms of DSS-induced colitis and reduces IL-6 gene expression." (PMID 33312339, 2020). "Drinking water with soybean-derived tripeptide VPY can reduce DAI, weight loss, MPO activity, and expressions of IL-1β, IL-6, IL-17, IFN-γ, and TNF-α in colitis mice, suggesting that VPY can treat IBD." (PMID 32963495, 2020). "IS exposure-induced colitis caused colon shortening and increased myeloperoxidase activity, TNF-α and IL-6 expression, and NF-κB activation in the colon." (PMID 32224881, 2020). "Those researchers found that rats receiving orally administrated propolis extract for 1 week prior to 3% DSS treatment showed decreased colitis and reduced inflammatory cytokine (IL-1β, IL-6, and MCP-1) levels." (PMID 32788877, 2020). "The subsequent induction and expression of various inflammatory cytokines (TNF-α, IL-6, IL1β, IL-17, and IFN-γ) and enzymes (iNOS and COX-2) that are associated with the initiation and development of colitis 49, 79 were also prevented by low-dose IL-2." (PMID 32308767, 2020). "In fact, inhibition in the production of TLR-4, NF-κB p65, COX-2, IL-17, TNF-α, IL-1β, and IL-6 is considered useful in treating colitis." (PMID 32848723, 2020). "In the current study, we found that alpinetin decreased the activation of NF-κB, the expression of pro-inflammatory mediator genes, the activity of MPO, and the production of TNF-α and IL-6 in DSS colitis mice." (PMID 32372959, 2020). "Our data from the DSS model of colitis also suggest a complex role of TNFα and IL-6 in intestinal inflammation." (PMID 33144591, 2020). "We have also shown the importance of IL-6 not only in tumor development, but also in the anti-inflammatory and reparative processes during colitis." (PMID 32867390, 2020). "Study has found that treatment with Cassia obtusifolia (CO) (1 g/kg) ameliorates signs including body weight loss and increased DAI, shortened colon length in DSS-induced colitis mice, as well as suppresses the levels of IL-6 and expression of COX-2." (PMID 32063999, 2020). "Meanwhile, the characteristics of colitis coupled with many other chronic inflammatory diseases are characterized with the production of more pro-inflammatory cytokines such as IL-6, IL-1β, and TNF-α in serum and tissue." (PMID 32670051, 2020). "Nicotine has also been shown to attenuate the severity of DSS colitis and expression of IL-6 in CD4T cells." (PMID 32855621, 2020). "The algae alkaloid caulerpin reduces DSS colitis by suppressing NF-κB activation and subsequently inhibiting the colonic production of TNFα, IFNγ, IL-6, IFNγ, and IL-17." (PMID 32855621, 2020). "Consistently, blockage of IL‐6/IL‐23 can protect the mice from colon damage and colitis‐induced death." (PMID 33240782, 2020). "Epicatechin has been shown to inhibit inflammation factors including TNF-α and IL-6 in mouse colitis and rat renal inflammation, while catechin can restrain the LPS-induced inflammation in BV-2 cells and human dental pulp cells." (PMID 32876071, 2020).
colitis (continued). "Ch25h−/− mice with DSS-induced colitis exhibited aggravated injury, including higher clinical colitis scores, severe injury of the epithelial barrier, lower tight junction protein levels and higher levels of IL-6." (PMID 32859970, 2020). "FLCWK can inhibit the activation of STAT3 by reducing the production of IL-6, thereby increasing the occurrence of colitis-related colorectal cancer with 5-FU." (PMID 33082817, 2020). "As DSS-induced colitis-like symptoms are reportedly accompanied by upregulation of pro-inflammatory cytokines, the plasma levels of IL-6, IL-1β, and TNF-α were examined." (PMID 32708415, 2020). "In a murine model of colitis-associated premalignant cancer, elevated expression of ADAM17, IL-6, gp130 and sIL-6R in lamina propria macrophages were reported." (PMID 32867390, 2020). "The production of TNF-α, IL-1β, and IL-6 plays leading roles in the initiation and progression of colitis, and some of them have been regarded as a logical target for IBD therapy." (PMID 33363184, 2020). "The induction of colitis by TNBS administration significantly attenuated IL-6 levels compared to the absolute control group, and likewise to the 50% EtOH vehicle group (35.84 ± 4.29 vs. 60.48 ± 4.55; 35.26 ± 2.96 vs. 60.48 ± 4.55 ng/L)." (PMID 32516975, 2020). "For example, sanguinarine and cavidine suppress the expression of NF-κB p65 subunit, thereby reducing colonic TNFα and IL-6 in acetic acid-induced colitis." (PMID 32855621, 2020). "Further experimental validation revealed that CSCC attenuated DSS-induced colitis by the suppression of the mRNA levels of IL-17A and of the cytokines it induces, such as IL-6, IL-1β, and TNF-α." (PMID 32382313, 2020). "Taken together, these results suggest the activation of the IL-6/STAT3 pathway in Ch25h−/− mice compared with WT mice upon DSS-induced colitis." (PMID 32859970, 2020). "In the TNBS mouse model of colitis, berberine reduces IFNγ, IL-1α, IL-6, IL-17, and TNFα expression in colonic tissues and sera and suppresses Th1 and Th17 cells through reduction of STAT1, STAT3, and NF-κB phosphorylation." (PMID 32855621, 2020). "Study reveals that APS (200 mg/kg) treatment increases weight and colon length and reduces NF-κB DNA phosphorylation activity and down-regulates TNF-α, IL-1β, IL-6, IL-17 expressions associated with improvement in DSS-induced mice colitis." (PMID 32063999, 2020). "Oral supplementation with 2-fucosyllactose significantly decreased the severity of colitis in IL-10−/− mice, reducing the expression of IL-1β and IL-6 and increasing TGF-β expression and expansion of the propionate-producing commensal Ruminococcus gnavus." (PMID 32429359, 2020). "The plant-derived alkaloid N-methylcytisine and the tea alkaloid theophylline mitigate colitis by downregulating TNFα, IL-1β, and IL-6 expression in DSS and acetic acid models of colitis, respectively." (PMID 32855621, 2020). "Administration of thalidomide significantly dose-dependently reduced the protein and mRNA expression levels of IL-23, IL-17, and IL-6 in the colonic tissue of TNBS-induced colitis rats." (PMID 32766176, 2020). "Apple polyphenols ameliorated DSS colitis and dampened the expression of proinflammatory transcripts, such as IL-6, IL-17, IL-22, and TNF-α." (PMID 33299531, 2020). "Subcutaneous administration of nicotine was shown to ameliorate tissue injury in DSS colitis and IL-6 expression in CD4T cells via α7-nAChRs." (PMID 32855621, 2020). "Pharmacological rescue of Dicer expression in an acute colitis mouse model alleviated inflammation in terms of final colon length, inflammatory cell infiltration, and cell apoptosis in colon tissues, and serum IL-6 levels." (PMID 32483416, 2020). "The level of pro-inflammatory cytokines (TNFα, IL-1β and IL-6) in the blood serum, as well as IL-1β in the colon tissue of mice with colitis receiving algae extract, was lower than that of control animals (pronounced manifestations of colitis)." (PMID 32486405, 2020).
colitis (continued). "Administration of B-naphtoflavone, an AhR agonist, improved DSS-induced colitis in mice and downregulated colitis-induced pro-inflammatory cytokines such as TNFα, IL6 and IL1β mRNA." (PMID 32957545, 2020). "Statistical analysis results show that the protein and mRNA expression levels of IL-23, IL-17, and IL-6 in the untreated TNBS-induced colitis group were significantly higher than those in the healthy control and thalidomide-treated groups (p < 0.05)." (PMID 32766176, 2020). "The mRNA expressions of IL1β and IL6 were dramatically reduced by inhibiting Ninj1 with the blocking peptide during the development of colitis." (PMID 31963519, 2020). "These components acted to protect mice against colitis inflammation by significantly suppressing cytokines [γ‐interferon (IFNγ), IL‐6,IL‐1β, and IL‐17a] related to colitis pathology and upregulating anti‐inflammatory cytokine IL‐10." (PMID 32410383, 2020). "One study in Smad3-/- colitis-prone mice found that in dietary DHA enhanced LPS-induced B-cell secretion of IL-6 and TNFα, and also increased CD40 expression versus controls." (PMID 33603741, 2020). "During the acute phase of colitis, plasma levels of IL-6 are increased, accompanied by activation of microglia, as well as increased levels of IL-1β, TNF-α, and p21 in the hippocampus." (PMID 32047521, 2020). "Exposure to EC also induced colitis in mice, causing colon shortening and increased myeloperoxidase activity, TNF-α and IL-6 expression, NF-κB activation, and infiltration of NF-κB/CD11c+ cells (activated DCs and macrophages) in the colon." (PMID 32224881, 2020). "For instance, green tea-derived polyphenol AcEGCG can protect against DSS-induced colitis by decreasing IL-1β, IL-6, TNF-α, and COX-2 productions and reducing NF-κB (p65 and IκBα) phosphorylation." (PMID 33664740, 2020). "For instance, ginseng extract has an anti-inflammatory effect by inhibiting NF-κB, consequently decreasing IL-6 in various stress models (heat stress and colitis models)." (PMID 32075045, 2020). "In acute DSS-induced colitis mice, the expression of IL-6, TNF-α elevated, and microglia was activated in the brain tissue." (PMID 32047521, 2020). "Colonic levels of the inflammatory cytokines TNF-α and IL-6 as markers of disease activity were measured by using western blot, which were significantly upregulated in the acute phase of colitis (day 7)." (PMID 31989391, 2020). "In colitis, continued stimulation of IL-6 activates STAT3 signaling, and is prone to modulating the Th17/Treg immune balance owing to Th17 responses." (PMID 33092149, 2020). "For example, IL-6 improves cellular proliferation and regulates crypt homeostasis in the intestine of murine colitis, while blockage of IL-6 exacerbates acute and late injury of the intestine after focal radiation." (PMID 33293477, 2020). "We observed that baicalein developed the secretion of TGF-β and suppressed the production of IL-6 in colitis mice." (PMID 33082710, 2020). "Concerning IL-6, its concentration was increased during colitis, while this increase was prevented by Emmental cheese consumption." (PMID 32156075, 2020). "Administration of Dab2-deficient DCs (DC2.4Dab2−/− cells) modulated the course of DSS colitis in wild-type mice, enhanced mucosal expression of Tnfa, Il6, and Il17a, and promoted neutrophil recruitment." (PMID 30873168, 2019). "We found that TOE attenuated the clinical symptoms, lowered the inflammatory scoring and inhibited the secretion of proinflammatory factors TNF‐α, IL‐1β and IL‐6 in DSS‐induced colitis." (PMID 31565850, 2019). "Further, addition of LPS significantly upregulated IL-6 in Nrf2−/− BMDM compared to wild-type BMDM as well as in TNBS-induced colitis model." (PMID 30626868, 2019). "A common feature of this acute colitis is the massive infiltration of innate immune cells that produce large amounts of pro-inflammatory mediators such as TNFα, IL-6, IL-1β, IL-23 and GMCSF." (PMID 31189465, 2019).